KMT5B (lysine methyltransferase 5B)
Description:
Histone methyltransferase that specifically methylates monomethylated 'Lys-20' (H4K20me1) and dimethylated 'Lys-20' (H4K20me2) of histone H4 to produce respectively dimethylated 'Lys-20' (H4K20me2) and trimethylated 'Lys-20' (H4K20me3) and thus regulates transcription and maintenance of genome integrity. In vitro also methylates unmodified 'Lys-20' (H4K20me0) of histone H4 and nucleosomes. H4 'Lys-20' trimethylation represents a specific tag for epigenetic transcriptional repression. Mainly functions in pericentric heterochromatin regions, thereby playing a central role in the establishment of constitutive heterochromatin in these regions. KMT5B is targeted to histone H3 via its interaction with RB1 family proteins (RB1, RBL1 and RBL2) (By similarity). Plays a role in myogenesis by regulating the expression of target genes, such as EID3. Facilitates TP53BP1 foci formation upon DNA damage and proficient non-homologous end-joining (NHEJ)-directed DNA repair by catalyzing the di- and trimethylation of 'Lys-20' of histone H4. May play a role in class switch reconbination by catalyzing the di- and trimethylation of 'Lys-20' of histone H4 (By similarity).
Synonyms: SUV420H1; CGI-85; CGI85; MRD51
Tractability: Small molecule: a structure with a bound ligand is known; a high-quality ligand is known. Antibody: its Gene Ontology location is reachable by antibodies, with high confidence; the Human Protein Atlas places it where antibodies can reach. PROTAC: UniProt records ubiquitination sites on it; ubiquitination databases record sites on it; a small molecule that binds it is known.
Target class: Writer; Protein methyltransferase; Epigenetic regulator
Chemical probes: A-196 (high quality)
Gene: Protein-coding gene on chromosome 11 (68,154,863 to 68,213,852, reverse strand). Ensembl gene ENSG00000110066.
Subcellular location: Nucleus; Chromosome
Subcellular location (Human Protein Atlas): Nucleoli fibrillar center; Nucleoplasm; Basal body; Centrosome; Cytokinetic bridge; Cytoplasmic bodies; Microtubules; Mitotic spindle; Plasma membrane; Primary cilium
Pathways (Reactome):
Chromatin organization: PKMTs methylate histone lysines
Gene Ontology:
Molecular function: chromatin binding; histone H4K20 methyltransferase activity; histone H4K20 monomethyltransferase activity; histone H4K20me methyltransferase activity; histone methyltransferase activity; protein binding; histone H4 methyltransferase activity; S-adenosyl-L-methionine binding
Biological process: DNA repair; positive regulation of double-strand break repair via nonhomologous end joining; positive regulation of isotype switching; chromatin remodeling
Cellular component: fibrillar center; nucleoplasm; nucleus; chromosome
Genetic constraint (gnomAD): Loss-of-function variants: 8 observed, 76.11 expected, observed/expected ratio (o/e) 0.11, 90% interval 0.061 to 0.19. The upper end of that interval is the gene's LOEUF score, 0.19, which puts it in group 1 of 6, group 1 being the genes least tolerant of losing a copy. Missense variants: 713 observed, 1,045.2 expected, observed/expected ratio (o/e) 0.68, 90% interval 0.64 to 0.73. Synonymous variants: 331 observed, 385.93 expected, observed/expected ratio (o/e) 0.86, 90% interval 0.78 to 0.94.
Gene-disease validity (ClinGen):
ClinGen rates the evidence that KMT5B causes each of these diseases.
complex neurodevelopmental disorder (autosomal dominant): Definitive. A disorder that involves more than one phenotype associated with the central nervous system, including but not limited to intellectual disability, autism, and seizures (epilepsy).
Homologues: Orthologues: chimpanzee KMT5B (99% identical), macaque KMT5B (99% identical), guinea pig KMT5B (91% identical), pig KMT5B (90% identical), dog KMT5B (88% identical), rat Kmt5b (87% identical), mouse Kmt5b (87% identical), rabbit KMT5B (78% identical), tropical clawed frog kmt5b (71% identical), zebrafish kmt5b (53% identical). Paralogues in human: KMT5C (23% identical).